RND1 (Rho family GTPase 1)
Diseases named in the same sentence as RND1 in open-access papers (continued):
Sharing a sentence is not in itself a finding about the gene and the disease.
tumor (12 papers, 2016 to 2024). "The impact of other RND1 mutations on its function and tumor initiation and progression remains to be determined." (PMID 31344837, 2019). "The loss of RND1 in mammary epithelial cells also contributes to tumor progression via (i) the induction of epithelial to mesenchymal transition (EMT), (ii) the induction of proliferation, and (iii) the ability to migrate and metastasize." (PMID 31344837, 2019). "RND1 is generally considered a tumor repressor, and its loss or aberrant expression in tumor cells may lead to tumor onset and development." (PMID 39129202, 2024). "In liver cancer, patients with lower levels of RND1 have larger tumor volumes and are more prone to microvascular invasion." (PMID 39129202, 2024). "Researchers investigated the tumor suppressor effect of RND1 in several tumors, and the influence of RND1 on EMT was discovered." (PMID 35505371, 2022). "Using Human Protein Atlas database, we investigated the expression levels of RND1 in various human normal tissues and tumor tissues." (PMID 35505371, 2022). "From the fluorescence, it was observed that tumor growth in Luc-RND1 group was significantly inhibited compared to that of the control group." (PMID 35505371, 2022). "These tumor progression effects induced by RND1 depletion are mediated through the activation of the Ras and MAPK pathways." (PMID 31344837, 2019). "Concerning the role of RND1 in tumor cell proliferation and migration, the results seem to be dependent on the tumor type." (PMID 31344837, 2019). "The alterations of RND1 expression in tumors and an in silico analysis that identified RND1 as a tumor suppressor gene suggest a potential role of RND1 in oncogenesis." (PMID 31344837, 2019). "Among the 23 analyzed tumor localizations, the hematological and lymphoid tissue is the tumor type for which the sensitivity to anticancer agents is the most dependent on the RND1 mRNA levels." (PMID 31344837, 2019). "We established an orthotopic xenograft tumor models to verify the effects of Rnd1 on HCC progression in vivo." (PMID 29706627, 2018). "Rnd1, a member of Rho GTPases, was found to be downregulated in human malignancies and downregulation of Rnd1 promotes tumor invasion via various mechanisms." (PMID 29706627, 2018). "The Fer-1 reversed tumor suppression induced by RND1 overexpression compared to Z-VAD-FMK and necrosulfonamide, suggesting that RND1 tumor inhibition of RND1 was not caused by apoptosis or necrosis, but by ferroptosis instead." (PMID 35505371, 2022). "The current research indicated that RND1 displays the characteristics of a tumor suppressor gene." (PMID 35505371, 2022). "By comparing the relative size and growth rate of tumors from both groups, it was observed that tumor growth of the nude mice was significantly inhibited in Luc-RND1 group compared with the control group, which was later confirmed by H&E staining of mouse brain sections." (PMID 35505371, 2022). "For several aggressive tumors, RND1 presents the features of a tumor suppressor gene." (PMID 31344837, 2019). "Furthermore, RND1 located up-stream of the up-regulated intergenic lncRNA, TCONS_00020413 is known to act as a tumor suppressor by attenuating Ras/MAPK signaling." (PMID 31324852, 2019). "This potential selective advantage of tumor cells suggests that inhibiting RND1-dependent signaling could sensitize them to CPT derivatives." (PMID 30209297, 2018). "According to this criteria, associations between Rnd1 expression and clinicopathologic characteristics of HCC were evaluated, the results showed that patients with low Rnd1 expression had a large tumor size, high incidence of microvascular invasion, and poor cell differentiation in tumor tissue." (PMID 29706627, 2018).
tumor (continued). "Additionally, IHC for serial slices of human tumor HCC tissue demonstrated that Rnd1 expression is positively correlated with E-cadherin (R = 0.563, P = 0.010) and negatively correlated with vimentin expression (R = −0.567, P = 0.009)." (PMID 29706627, 2018). "Based on previous experience, we speculated that RND1 acted as a tumor repressor in LUSC." (PMID 39129202, 2024). "We speculated that RND1 may exert a tumor‐repressive role in LUSC." (PMID 39129202, 2024). "There is a correlation between RND1 and cell migration in GBM stem cells, and several studies have shown that the sensitivity of tumor cells to ferroptosis depends on their EMT status." (PMID 35505371, 2022). "The mRNA expression level of Rnd1 was compared in 20 paired HCC tissue and adjacent non-tumor liver tissue (ANLT)." (PMID 29706627, 2018). "We therefore selected EZH2 target genes with tumour‐suppressive functions (KLF2, RND1 or PTEN) that could be involved in the link between SNHG7 and OC progression." (PMID 32420685, 2020). "Next, we selected several EZH2, LSD1 or DNMT1 potential targets (P15, P21, LATS2, RND1, KLF2, NKD2, PTEN) with tumor-suppressor function and SPRY4, and hypothesized that they may involve in the contributions of SPRY4-IT1 to CCA progression." (PMID 29642935, 2018). "Considering that Rnd1 is frequently silenced in HCC, generating specific inhibitors for Rnd1 methylation may achieve stronger tumor-selective toxicity than traditional drugs." (PMID 29706627, 2018). "Moreover, according to tumor cell type, positive and negative correlation between the levels of RND1, and the sensitivity to EGFR inhibitors can be found." (PMID 31344837, 2019). "Furthermore, we chose several EZH2 or LSD1 potential targets (P15, P21, LATS1, LATS2, RND1, KLF2, E-cadherin, PTEN, ASPP2 and RRAD) with tumor-suppressor function, and hypothesized that they may involve in the contributions of AGAP2-AS1 to NSCLC progression." (PMID 27195672, 2016). "In addition, for patients who do not respond to standard therapy, the RND1 rate in tumor biopsies could be helpful in selecting the most appropriate targeted therapy for each patient." (PMID 31344837, 2019).
cancer (9 papers, 2010 to 2024). A tumor composed of atypical neoplastic, often pleomorphic cells that invade other tissues. "As assayed by qPCR, RND1 was significantly downregulated in three cancer cell lines compared to the normal cell line." (PMID 39129202, 2024). "In LUSC, increased miR‐4652‐5p lowered RND1 expression and facilitated the malignant progression of cancer cells." (PMID 39129202, 2024). "It is worth noting that current research on RND1 in cancer mainly focuses on phenotypic studies such as EMT, while research on drug resistance is relatively limited." (PMID 39129202, 2024). "Because research on RND1 in cancer mainly focuses on the cell phenotype of EMT, we studied RND1’s effect on lipid oxidation in GBM cells and its regulation mechanism in ferroptosis." (PMID 35505371, 2022). "All these proliferation and migration data show that a dysregulation of the amount of RND1 (either overexpression or decreased expression) in cancer cells increases the proliferation and migratory capacity of these cells." (PMID 31344837, 2019). "Oct4 binds to the promoter of RND1 on two sites (−844 and −1271 bp) and this binding inhibits RND1 transcription in the human cancer MDA-MB231 cell line." (PMID 31344837, 2019). "This discrepancy concerning the role of RND1 in invasion is correlated with the difference of RND1 misregulation in these cancers." (PMID 30333910, 2018). "Like other Rho GTPases, the transcript of RND1 is aberrant in cancer." (PMID 39129202, 2024). "Overexpression of RND1 suppressed cancer cell proliferation." (PMID 39129202, 2024). "Research is still needed to identify upstream modulatory genes of RND1 in cancer induction." (PMID 39129202, 2024). "The molecular mechanism of RND1 in cancer is currently less reported, and its abnormal expression may be manipulated via epigenetic mechanisms." (PMID 39129202, 2024). "In Section 3, the repression of increased RND1 on cancer cell progression was confirmed." (PMID 39129202, 2024). "Besides the roles of RND1 in healthy tissues, recent data suggest that RND1 is involved in oncogenesis and response to cancer therapeutics." (PMID 31344837, 2019). "Regarding the induction of RND1 expression in cancers, there are fewer data in the literature." (PMID 31344837, 2019). "As other Rho GTPases, the expression of RND1 transcripts is altered in cancers." (PMID 31344837, 2019). "This necessitates the molecular mechanisms linking RND1 to cancer cell sensitivity." (PMID 31344837, 2019). "These experiments indicated that FOXA2 was an upstream regulator of RND1, thus affecting the DDP resistance of cancer cells." (PMID 39129202, 2024).
infection (4 papers, 2013 to 2022). The state of being infected such as from the introduction of a foreign agent such as serum, vaccine, antigenic substance or organism. "Next, we overexpressed Rnd1 in Hela cells followed by infection with LM and tested relative expression by RT-PCR or measured indicated cytokine by ELISA." (PMID 35654795, 2022). "The induction of the expression of TCIM and RND1 was also previously determined after infection of HIBCPP cells with NmB." (PMID 34863201, 2021). "We observed that Rnd1 overexpression decreased viral and bacterial load even after 1 h post-infection, suggesting Rnd1 may affect microbial internalisation." (PMID 35654795, 2022). "Finally, we verified the relevance of these results in-vivo by knocking down Rnd1 in mice followed by infection with PR8 or Listeria." (PMID 35654795, 2022).
bacterial infection (1 paper, 2022). "Here, we have compared the innate immune responses between humans and bats to identify a novel membrane-associated protein, Rnd1, which defends against viral and bacterial infection in an interferon-independent manner." (PMID 35654795, 2022). "We show that Rnd1 is induced by pro-inflammatory cytokines during viral and bacterial infections and provides protection against these pathogens through two distinct mechanisms." (PMID 35654795, 2022). "Previously it has been reported that Rnd1 is localised on the plasma membrane, and therefore, it was speculated that Rnd1 might be crucial in internalisation during viral and bacterial infection." (PMID 35654795, 2022).
RND1 also shares sentences with these, for which no sentence is quoted: adenoid cystic carcinoma (1 paper); colon carcinoma (1); listeria infection (1); lung carcinoma (1); lymphoid tumors (1); triple-negative breast carcinoma (1).